MOV10L1 (Mov10 like RNA helicase 1)
Description:
ATP-dependent 5'-3' RNA helicase required during spermatogenesis to repress transposable elements and prevent their mobilization, which is essential for germline integrity. Acts via the piRNA metabolic process, which mediates the repression of transposable elements during meiosis by forming complexes composed of piRNAs and Piwi proteins and governs the methylation and subsequent repression of transposons. Involved in the primary piRNA metabolic process. Specifically binds to piRNA precursors and promotes the generation of intermediate piRNA processing fragments that are subsequently loaded to Piwi proteins. Acts via its ATP-dependent RNA helicase activity: displays 5'-3' RNA unwinding activity and probably mediates unwinding and funneling of single-stranded piRNA precursor transcripts to the endonuclease that catalyzes the first cleavage step of piRNA processing to generate piRNA intermediate fragments that are subsequently loaded to Piwi proteins.
Synonyms: DJ402G11.8; DKFZp434B0717; CHAMP; SPGF73
Tractability: No criterion of Open Targets' tractability assessment is met for any kind of drug.
Gene: Protein-coding gene on chromosome 22 (50,090,006 to 50,161,690, forward strand). Ensembl gene ENSG00000073146.
Subcellular location: Cytoplasm
Pathways (Reactome):
Gene expression (Transcription): PIWI-interacting RNA (piRNA) biogenesis
Gene Ontology:
Molecular function: ATP binding; ATP hydrolysis activity; magnesium ion binding; RNA binding; RNA helicase activity; 5'-3' RNA helicase activity; helicase activity
Biological process: germ cell development; spermatogenesis; male meiosis I; piRNA processing; transposable element silencing by piRNA-mediated DNA methylation
Cellular component: cytoplasm; cytosol; P granule; pi-body
Genetic constraint (gnomAD): Loss-of-function variants: 89 observed, 121.9 expected, observed/expected ratio (o/e) 0.73, 90% interval 0.61 to 0.87. The upper end of that interval is the gene's LOEUF score, 0.87, which puts it in group 3 of 6, group 1 being the genes least tolerant of losing a copy. Missense variants: 1,276 observed, 1,428.7 expected, observed/expected ratio (o/e) 0.89, 90% interval 0.85 to 0.94. Synonymous variants: 542 observed, 545.69 expected, observed/expected ratio (o/e) 0.99, 90% interval 0.93 to 1.07.
Homologues: Orthologues: chimpanzee MOV10L1 (97% identical), macaque MOV10L1 (96% identical), dog MOV10L1 (81% identical), mouse Mov10l1 (81% identical), rat Mov10l1 (80% identical), guinea pig MOV10L1 (79% identical), rabbit MOV10L1 (75% identical), tropical clawed frog mov10l1 (57% identical), Drosophila melanogaster CG6701 (20% identical), Drosophila melanogaster Mov10 (17% identical), zebrafish setx (14% identical), Caenorhabditis elegans Y106G6D.5 (10% identical), and 2 more. Paralogues in human: MOV10 (25% identical), HELZ (19% identical), HELZ2 (18% identical), SETX (16% identical), AQR (15% identical), ZNFX1 (14% identical), DNA2 (14% identical), UPF1 (12% identical), IGHMBP2 (12% identical), CT55 (11% identical).
Diseases named in the same sentence as MOV10L1 in open-access papers:
MOV10L1 is named in the same sentence as 10 diseases in open-access papers, as found by Europe PMC text mining. Sharing a sentence is not in itself a finding about the gene and the disease. The quoted sentences say what the papers report.
Infertility (3 papers, 2021 to 2024). "Given the sensitivity to gene dosage and the essential functions of these target genes, increased miRNA-guided AGO2-mediated cleavage of their transcripts and decreased protein synthesis may contribute to the infertility of Mov10l1 CKO mutants." (PMID 34645830, 2021). "Spermatocytes from mice homozygous for a targeted deletion of the helicase domain of Mov10l1 (Mov10l1-/-) arrest early in meiosis leading to a complete lack of post-meiotic germ cells, hypogonadism and infertility." (PMID 33635934, 2021).
male infertility (2 papers, 2015 to 2021). The inability of the male to effect fertilization of an ovum after a specified period of unprotected intercourse. "Constitutive inactivation of MOV10L1 by deletion of the helicase domain leads to loss of mature piRNAs, de-repression of retrotransposons, arrest during meiotic prophase, and male infertility." (PMID 33635934, 2021). "Polymorphisms in MOV10L1 have been associated with azoospermic male infertility." (PMID 26221191, 2015). "Point mutations in MOV10L1 may thus contribute to male infertility in humans." (PMID 33635934, 2021).
Hepatitis (1 paper, 2024). Inflammation of the liver. "Strong associations have been found between viruses in plasma, hepatitis, and MOV10L1 expression." (PMID 38396502, 2024).
sterility (1 paper, 2021). "Male Mov10l1–/– sterility could be expected, but female Mov10l1–/– sterility was surprising given the normal fertility of female Mov10l1–/– mice." (PMID 34489573, 2021).
tumours (1 paper, 2022). "In a subsample of patients whose tumours were profiled for RNA (n = 96), feature S(1,−1)SumAverg was significantly associated with the expression of gene MOV10L1, LRP1B, ZFY, PITX2, TRAPPC12, MMGT1 and PPP2R2C (all P < 0.05)." (PMID 36050449, 2022).
MOV10L1 also shares sentences with these, for which no sentence is quoted: Azoospermia (2 papers); Cardiovascular Disease (1); hypogonadism (1); Nephroblastoma (1); Temple syndrome (1).